TM4SF5 (transmembrane 4 L six family member 5)
Diseases named in the same sentence as TM4SF5 in open-access papers (continued):
Sharing a sentence is not in itself a finding about the gene and the disease.
colon carcinoma (continued). "However, the use of peptide vaccines in combination with TM4SF5 mAb significantly reduced metastatic colon cancer in mice." (PMID 34193050, 2021). "In addition, the trends in the dissemination of HCT-116 cells mediated by TM4SF5 or its C-terminus were also observed in HT29 colon cancer cells stably infected with the constructs." (PMID 28129652, 2017). "Importantly, we found that the cyclic peptide vaccine and the humanized anti-TM4SF5 antibody suppressed the formation and growth of lung metastases, which were established by intravenous injection of colon cancer cells in a mouse metastasis model." (PMID 27816969, 2016). "Therefore, we conclude that the immunization with the cyclic peptide vaccine and injection of the TM4SF5-specifc humanized antibody have an anti-metastatic effect against colon cancer in mice." (PMID 27816969, 2016). "Here, we isolated a novel monoclonal antibody targeting a structural epitope of TM4SF5, a protein that induces EMT, proliferation, and metastasis in cancer, and evaluated TM4SF5 as a target of immunotherapy to suppress metastasis of colon cancer in a mouse model." (PMID 27816969, 2016). "It has been reported that TM4SF5 mRNA is expressed in colon carcinoma, pancreatic tumors, and HCC." (PMID 25268742, 2014). "Therefore, we suggest that the TM4SF5-specific monoclonal antibody has a therapeutic effect against colon cancer." (PMID 25268742, 2014). "In addition, we investigated in vitro and in vivo effects of anti-TM4SF5 antibody using colon cancer cell lines and mouse models." (PMID 25268742, 2014). "Here, we investigated expression of TM4SF5 in 45 primary colon cancer tissues." (PMID 25268742, 2014). "We then investigated the effect of the anti-TM4SF5 monoclonal antibody on colon cancer cell growth." (PMID 25268742, 2014). "The expression of TM4SF5 in some colon cancer cell lines was also examined." (PMID 25268742, 2014). "Nonetheless, we can conclude that the anti-TM4SF5 antibody may have therapeutic effects on colon cancer." (PMID 25268742, 2014). "In addition to HCC, TM4SF5 expression was also detected in colon cancer and pancreatic cancer tissues." (PMID 25268742, 2014). "However, some mechanisms of action induced by anti-TM4SF5 antibody in colon cancer appear to be different from HCC." (PMID 25268742, 2014). "Therefore, the anti-hTM4SF5 monoclonal antibody can target colon tumor cells expressing TM4SF5 in vivo." (PMID 25268742, 2014). "It is thus concluded that expression of TM4SF5 can serve as a marker of colon cancer." (PMID 25268742, 2014). "However, almost all of the colon cancer tissues (44 among 45 samples) expressed TM4SF5 (97.8%, staining in >11% of tumor cells)." (PMID 25268742, 2014). "Therefore, we conclude that the anti-TM4SF5 antibody has an anti-proliferative effect on human colon cancer cells expressing TM4SF5 in vitro." (PMID 25268742, 2014). "The TM4SF5-specific monoclonal antibody could inhibit colon cancer growth in a mouse model." (PMID 26621839, 2016). "Previously, we observed that high levels of TM4SF5 correlated with worse overall survival of CRC patients, suggesting a potential role for TM4SF5 in colon cancer progression." (PMID 35211652, 2022). "In a previous study, we demonstrated the prophylactic and therapeutic effects of a TM4SF5-specific peptide vaccine and monoclonal antibody in HCC and colon cancer in a mouse model." (PMID 27816969, 2016). "We showed that a peptide vaccine composed of liposome-encapsulated CpG-DNA and a B-cell epitope, predicted from the amino acid sequence of TM4SF5, contributed to prevention and therapy of HCC and colon cancer in a mouse model." (PMID 27816969, 2016). "Previously, we reported that TM4SF5 can be a therapeutic target of vaccination for HCC and colon cancer." (PMID 27816969, 2016).
colon carcinoma (continued). "To evaluate the significance of TM4SF5 as a target in colon cancer metastasis control in mice, we first immunized BALB/c mice with the TM4SF5 peptide vaccine composed of the cyclic TM4SF5 peptide (hTM4SF5EC2-C) and Lipoplex(O)." (PMID 27816969, 2016). "Using this technology, we showed that TM4SF5 can serve as a molecular target for HCC and colon cancer: a peptide vaccine targeting TM4SF5 had preventive or therapeutic effects against HCC and colon cancer in mouse models." (PMID 25268742, 2014). "Furthermore, we produced a monoclonal antibody that specifically recognizes human and mouse TM4SF5 and confirmed that the anti-TM4SF5 monoclonal antibody has a therapeutic effect in mouse models for HCC and colon cancer." (PMID 27816969, 2016). "Therefore, it is highly possible that a TM4SF5-specific peptide vaccine and an anti-TM4SF5 monoclonal antibody can be valuable agents in clinical management of HCC and colon cancer metastases." (PMID 27816969, 2016). "Anti-TM4SF5 chimeric and humanized monoclonal antibodies were generated and found to efficiently suppress tumor growth in nude mice bearing liver or colon cancer xenografts, without generating general toxicity, suggesting that these antibodies have potential as novel therapeutic agents." (PMID 35211652, 2022). "Therefore, we checked these aspects and found that anti-TM4SF5 did not induce a prominent change in colon cancer cells (data not shown)." (PMID 25268742, 2014). "However, the levels of TM4SF5 expression did not correlate with colon tumor grade or stage." (PMID 25268742, 2014).
liver diseases (7 papers, 2013 to 2025). "Altogether, these findings suggest that TM4SF5-mediated STAT3 activity for extracellular matrix modulation is involved in the progression of liver disease to HCC and that TM4SF5 appears to suppress NK cells during liver carcinogenesis." (PMID 34921636, 2021). "In the future, we can address the roles of TM4SF5 in hepatocytes and how this protein contributes to liver disease for the purposes of development of antifibrotic reagents that are therapeutically promising." (PMID 28458469, 2017). "Based on previous reports of TM4SF5‐mediated liver diseases, we investigated whether TM4SF5 expression could elicit biological effects in animals." (PMID 36063136, 2022). "Thus, TM4SF5 (as a molecule to suppress NK surveillance) is a promising target for the treatment of advanced liver diseases." (PMID 34921636, 2021). "Because we showed that hepatic fibrosis/cirrhosis and cancer involves TM4SF5, blockade of TM4SF5 function/activity may be a beneficial strategy for the treatment of TM4SF5-dependent liver diseases." (PMID 34921636, 2021). "Importantly, TM4SF5 functionally contributes to liver diseases including metabolic disorders, inflammation, and fibrosis of the liver." (PMID 28458469, 2017). "We next examined how TM4SF5 expression could differ depending on the liver disease status." (PMID 37670786, 2023). "TM4SF5 is involved in the development of NAFLD21 and portal hypertension." (PMID 37670786, 2023).
colorectal cancer (3 papers, 2022 to 2025). A primary or metastatic malignant neoplasm that affects the colon or rectum. "Elevated metastasis-associated in colon cancer 1 (MACC1) expression in colorectal cancer patients, and high transmembrane 4 L6 family member 5 (TM4SF5) protein expressed on various solid tumors’ surface, are linked to aggressive cancer behavior and progression." (PMID 39273182, 2024). "Transmembrane 4 L6 family member 5 (TM4SF5) protein is highly expressed in various solid tumors, including colorectal cancer (CRC), where it has been reported to be overexpressed in 58% of cases." (PMID 39273182, 2024). "The transmembrane 4 L six family member 5 (TM4SF5) is aberrantly expressed in hepatocellular and colorectal cancers, and has been implicated in tumor progression, suggesting that it could serve as a novel therapeutic target." (PMID 35211652, 2022).
idiopathic pulmonary fibrosis (3 papers, 2019 to 2021). Idiopathic pulmonary fibrosis (IPF) is a nonneoplastic pulmonary disease that is characterized by the formation of scar tissue within the lungs in the absence of any known cause. "Through its interactions with cysteine transporters, TM4SF5 appears to contribute to hormetic production of damaging chemicals that can cause the tissue scarring underlying idiopathic pulmonary fibrosis." (PMID 31956272, 2020). "We postulated that TM4SF5 and its associated molecules were critically involved in pulmonary fibrosis." (PMID 31501417, 2019). "Primary AEC cultures were analyzed for biomarkers of AECI or AECII to evaluate further the AEC type involved in the TM4SF5-protective effects in response to bleomycin-induced pulmonary fibrosis." (PMID 31501417, 2019). "Intratracheal injection of bleomycin was administrated to wild-type and Tm4sf5-knockout (Tm4sf5−/−) mice to induce pulmonary fibrosis." (PMID 31501417, 2019). "Tm4sf5-null mice exhibited attenuated bleomycin-induced pulmonary fibrosis with lower CD44v8-10 and ESRPs levels than wild-type mice." (PMID 31501417, 2019). "Next, we explored the physiological function of TM4SF5-mediated regulation of intracellular ROS in lung epithelial cells of mice treated with bleomycin to induce pulmonary fibrosis." (PMID 31501417, 2019). "In lung epithelial cells, TM4SF5 expression leads to suppression of ZEB2, which in turn increases alternative splicing factors for CD44 isoforms (from the standard CD44 form to CD44v8-10 variant form) during idiopathic pulmonary fibrosis." (PMID 34921636, 2021). "As a result, Tm4sf5-knockout C57BL/6 mice have ameliorated bleomycin-induced lung fibrosis compared to the fibrosis in Tm4sf5-expressing wild type mice, in which the architecture of the lung epithelium is disrupted, leading to the accelerated death of type I AECs and hyperplasia of type II AECs." (PMID 31956272, 2020). "TM4SF5 and CD44v80-10 are therefore promising targets for the treatment of pulmonary fibrosis." (PMID 31956272, 2020). "In addition, further investigation is warranted to determine if TM4SF5 modulates intracellular ROS during pulmonary fibrosis." (PMID 31501417, 2019). "Therefore, TM4SF5 mediates hormetic levels of intracellular ROS as demonstrated by the bleomycin-induced pulmonary fibrosis model." (PMID 31501417, 2019). "Primary mouse alveolar epithelial cells (AECs) revealed type II AECs (AECII), but not type I, to adapt the TM4SF5-mediated characteristics, suggesting TM4SF5-mediated AECII survival following AECI injury during idiopathic pulmonary fibrosis (IPF)." (PMID 31501417, 2019). "Intratracheal injection of bleomycin into wild-type C57BL/6 mice induces severe pulmonary fibrosis to generate an experimental model for IPF, whereas administration of bleomycin into Tm4sf5-knockout mice shows reduced progression of fibrotic phenotypes and increased survival of mice." (PMID 31956272, 2020). "However, this TM4SF5-mediated mechanism and its corresponding phenotype were observed in primary AECII, but not in AECI, in a bleomycin-induced pulmonary fibrosis animal model." (PMID 31501417, 2019).
Insulin resistance (3 papers, 2022 to 2023). Increased resistance towards insulin, that is, diminished effectiveness of insulin in reducing blood glucose levels. "Next, we explored how hepatocyte TM4SF5 expression might regulate fructose or glucose uptake in the context of insulin resistance." (PMID 35123128, 2022). "In addition, analyses using liver and serum samples from non-NAFLD, NAFLD-NASH, and NASH-Cirrhosis patients revealed that TM4SF5 tended to increase as NAFLD developed along with serum apelin level enhancement, insulin resistance, and cholesterol enrichment." (PMID 37670786, 2023). "Meanwhile, over their life spans, KO and WT mice did not exhibit any significant differences in insulin resistance whereas Tm4sf5 levels were declined after approximately 6 months of age." (PMID 36063136, 2022).
liver fibrosis (3 papers, 2014 to 2021). "This study provides evidence that TM4SF5-mediated STAT3 signaling promoted collagen I and laminin expression, which were involved in hepatic fibrosis/cirrhosis and eventual carcinogenesis in TM4SF5-transgenic and chemically induced mouse models." (PMID 34921636, 2021). "During these TM4SF5-mediated processes that contribute to liver fibrosis and cancer development, it seems that this tetraspanin, TM4SF5, plays important roles in the regulation of cellular functions related to the diseases via signal transduction." (PMID 28458469, 2017). "This study revealed that TM4SF5 levels were positively correlated with CD151 expression but were negatively with CD63 expression during liver fibrosis and tumorigenesis." (PMID 25033048, 2014). "We investigated the relationship between TM4SF5-positive TEMs with liver fibrosis and tumorigenesis, using normal Chang hepatocytes that lack TM4SF5 expression and chronically TGFβ1-treated Chang cells that express TM4SF5." (PMID 25033048, 2014). "Although TM4SF5 is involved in animal liver fibrosis and xenograft growth, the mechanism by which TM4SF5 is influenced by the immune system, particularly via NK cells, during hepatic carcinogenesis remains unknown." (PMID 34921636, 2021). "Although transmembrane 4 L six family member 5 (TM4SF5) is involved in liver fibrosis and cancer, its mechanism avoiding immune surveillance during carcinogenesis remains unknown." (PMID 34921636, 2021). "Here, we have discussed the effects of TM4SF5 expression on hepatocytes during liver fibrosis." (PMID 28458469, 2017). "We found that TM4SF5 expression could override CD151 functions, and TM4SF5 acted antagonistically to CD63 during liver fibrosis development and during hepatic migration/invasive extracellular matrix (ECM) -degradation." (PMID 25033048, 2014). "Therefore, TM4SF5 is an important player during TGFβ1 and soluble factor-mediated activation of liver cells, because it regulates ECM production and contributes to the development of liver fibrosis." (PMID 28458469, 2017). "TM4SF5 expression correlates with α-SMA expression in the liver of CCl4-treated mice, possibly indicating an EMT process and/or hepatic stellate cell (HSC) activation, although an EMT process during liver fibrosis has not been confirmed in vivo." (PMID 28458469, 2017).
pancreatic cancer (3 papers, 2012 to 2017). "TM4SF5 was identified as a tumor-associated antigen, similar to L6 which is a lung tumor-associated antigen, via a large-scale screen for differentially expressed genes in pancreatic cancer in 1998." (PMID 28458469, 2017). "Considering that TM4SF5 expression was detected also in pancreatic cancer tissues, we can extend the present research to investigate the expression of TM4SF5 protein in a number of pancreatic cancer tissues and evaluate the efficacy of the anti-TM4SF5 antibody as a therapeutic in a mouse model." (PMID 25268742, 2014).
Cirrhosis (2 papers, 2021 to 2023). A chronic disorder of the liver in which liver tissue becomes scarred and is partially replaced by regenerative nodules and fibrotic tissue resulting in loss of liver function. "In addition, public Gene Expression Omnibus (GEO) data analysis showed that TM4SF5 expression was highly elevated in HCC patients, and these elevated levels were negatively correlated with SOCS1 expression in both cirrhosis and HCC patients compared with the normal population." (PMID 34921636, 2021).
esophageal cancer (2 papers, 2014 to 2022). A primary or metastatic malignant neoplasm involving the esophagus. "TM4SF5 is aberrantly expressed in liver, colon, lung, pancreatic, and esophageal cancers, and its high expression is associated with a poor prognosis." (PMID 35211652, 2022). "Recently, high expression of TM4SF5 in esophageal cancer tissues was reported: a high level of TM4SF5 expression was detected in about 45% of evaluated cases and high TM4SF5 expression was associated with cancer progression and poor patient survival." (PMID 25268742, 2014). "It is thus possible that anti-TM4SF5 antibody also has anti-cancer effects on esophageal cancer." (PMID 25268742, 2014).
Hepatic steatosis (2 papers, 2022 to 2023). Steatosis is a term used to denote lipid accumulation within hepatocytes. "We found that GLUT8 plays roles in fructose uptake and metabolism in hepatocytes via changes in its intracellular locations, depending on the expression of and its binding to TM4SF5, during high-fructose diet for hepatic steatosis." (PMID 35123128, 2022). "Finally, this study provides evidence that TM4SF5 expression in hepatocytes can promote abnormal food-intake behaviors such as increased eating during inappropriate mealtimes, which is supported by TM4SF5-mediated apelin expression, leading to initiation of hepatic steatosis toward NAFLD features." (PMID 37670786, 2023). "These TM4SF5-mediated effects involved DNL through hepatocyte accumulation of lipids, including acylglycerols and cholesterols, for hepatic steatosis." (PMID 35123128, 2022). "We focused on the roles of TM4SF5 in non-alcoholic fatty liver and/or abdominal obesity, after observations on abdominal obesity and NASH in the TM4SF5-genetic animal models." (PMID 35123128, 2022). "Thus, TM4SF5 and/or GLUT8 may be promising treatment targets against liver steatosis resulting from excessive fructose consumption." (PMID 35123128, 2022).
lung carcinoma (2 papers, 2014 to 2022). "TM4SF5-mediated EMT may have an important function in the resistance of lung cancer cells to EGFR kinase inhibitors (e.g., gefitinib)." (PMID 35211652, 2022). "Therefore, TM4SF4 functions in cancer, especially in lung cancer, have not been studied, although other members of the tetraspanin L6 family, such as TM4SF1 and TM4SF5, have been investigated as inducers of tumorigenesis." (PMID 25344917, 2014).
metabolic dysfunction-associated steatotic liver disease (2 papers, 2022 to 2026). Metabolic dysfunction-associated steatotic liver disease (MASLD, formerly known as nonalcoholic fatty liver disease or NAFLD) is a type of liver disease that is not caused by alcohol. "Transmembrane 4 L six family member 5 (TM4SF5) is implicated in metabolic dysfunction-associated steatotic liver disease (MASLD)." (PMID 41608638, 2026). "In addition, TM4SF5 has been shown to be involved in non‐alcoholic fatty liver disease." (PMID 36063136, 2022).
Glucose intolerance (1 paper, 2022). Glucose intolerance (GI) can be defined as dysglycemia that comprises both prediabetes and diabetes. "Further, the higher glucose intolerance observed in KO mice compared to WT mice at 3 months of age improved after the injection of liv/hep‐sEVTm4sf5‐HA from Alb‐Tm4sf5 TG mice." (PMID 36063136, 2022). "We found that TM4SF5 deficiency led to glucose intolerance without any influence by insulin, presumably leading to the healthy regulation of BW, which was achieved by sEVTm4sf5 derived from hepatocytes targeting BAT for efficient energy usage and blood glucose clearance." (PMID 36063136, 2022).
melanoma (1 paper, 2022). A malignant, usually aggressive tumor composed of atypical, neoplastic melanocytes. "Ab27 bound to HCT-116, HT-29 (colon), SNU-398 (liver), SNU-638 (stomach), and C8161 (melanoma) cancer cells expressing endogenous TM4SF5, and suppression of TM4SF5 expression by siRNA decreased Ab27 binding to these cells, confirming the specificity of Ab27." (PMID 35211652, 2022).
metastatic tumors (1 paper, 2016). "The humanized anti-TM4SF5 antibody reduced the growth of lung metastatic tumors, as measured by changes in tumor volume and weight, compared to that in human IgG-injected mice." (PMID 27816969, 2016).
non-alcoholic steatohepatitis (1 paper, 2022). "Systemic TM4SF5 overexpression in mice promotes non-alcoholic steatohepatitis (NASH)-associated fibrosis via alternative signal transduction in hepatocytes." (PMID 35123128, 2022). "Transmembrane 4 L six family member 5 (TM4SF5) is likely involved in non-alcoholic steatohepatitis, although its roles and cross-talks with glucose/fructose transporters in phenotypes derived from high-carbohydrate diets remain unexplored." (PMID 35123128, 2022).